C3 (complement C3)
Diseases named in the same sentence as C3 in open-access papers (continued):
Sharing a sentence is not in itself a finding about the gene and the disease.
autoimmune disease (62 papers, 2005 to 2026). A disorder resulting from loss of function or tissue destruction of an organ or multiple organs, arising from humoral or cellular immune responses of the individual to their own tissue constituents. "Younger patients were also more likely to report involuntary weight loss, C3 complement consumption, inflammatory arthralgia, Raynaud’s phenomenon, anemia, family history of autoimmune diseases, and overlap with SLE." (PMID 40650238, 2025). "IgAN is an autoimmune disease associated with complement activation, and extensive research has shown that hyperuricemia and the deposition of C3 are independent risk factors for IgAN progression." (PMID 38650643, 2024). "Among known classical complement receptors (CR), only type 1 complement receptor (CR1/CD35) was shown to bind both C4b and C3b fragments of cleaved C4 and C3 using two different domains for C4b and C3b, and this receptor is associated with the pathogenesis of certain autoimmune diseases." (PMID 37234916, 2023). "For example, a low measured CH50, reciprocal for 50% hemolysis, low levels of C3 and C4, and a normal factor B value, are indicative for classical pathway activation implicated in autoimmune disorders like Sjogren’s syndrome, systemic lupus erythematosis (SLE), or rheumatoid arthritis." (PMID 34943212, 2021). "In a similar manner, studies in mouse in vivo models of various autoimmune diseases demonstrated that IgG mediated tissue inflammation was blocked in mice deficient in activating FcγRs, although the complement component C3 was still abundantly deposited in the tissue." (PMID 26185769, 2015). "A recent study in autoimmune disease suggests that the elevated levels of immune complexes (ICs) are associated with increased levels of IgG1 and decreased levels of C3 and C4 in cases of autoimmune pancreatitis, since IgG1 is a molecule capable of activation of the classical pathway." (PMID 23941472, 2013). "One group has generated a floxed C3 IRES-tdTomato reporter mouse which was crossed with a Cre-Deleter mouse on a C57BL/6 background to investigate the role of C3 in autoimmune diseases." (PMID 40678242, 2025). "If BSS is suspected in a patient, the presence of autoimmune diseases, as well as low serum C3 and detectable C3 nephritic factor helps in confirming the diagnosis alongside the regionality of lipoatrophy." (PMID 40126619, 2025). "All patients were positive in Coombs test, patient 1 had positive c-ANCA, and patient 3 had positive ANA and β2GP I with reduced complement C3 levels, which indicated autoimmune disease." (PMID 34620178, 2021). "Monitoring serum levels of C3 to assess for disease activity is recommended in patients with autoimmune diseases, in particular APS." (PMID 31824513, 2019). "Various trigger events associated with aHUS have been reported previously, including infections, drugs, malignancy, pregnancy, or autoimmune diseases such as systemic lupus erythematous, C3 nephritic factor, and anticardiolipin." (PMID 26911616, 2016). "In comparison to C3 and C4, where levels represent the net rate of production and consumption, this assay measures a cleavage neoepitope solely exposed during complement activation and it has proven valuable as a biomarker in another autoimmune disease." (PMID 40440129, 2025). "Serum C3, as an enzyme-active globulin, plays a key role in immune regulation, clearing immune complexes, stabilizing the internal environment of the body, and participating in allergic reactions and autoimmune diseases." (PMID 39765473, 2024). "In addition, measuring complement C3 serum levels is a routine practice to monitor disease activity in patients with autoimmune diseases." (PMID 31824513, 2019). "Suppression of apoptotic cell disposal by Ab against deposited C3 may contribute to increasing severity and/or exacerbations in different autoimmune diseases." (PMID 30761135, 2019).
autoimmune disease (continued). "The complement system, particularly complement C3, plays a critical role in autoimmune diseases, and a decrease in complement C3 levels not only indicates increased disease activity but may also lead to an imbalance in immune regulation, exacerbating autoimmune responses." (PMID 40366475, 2025). "Given that C3 is the convergent point of all three complement cascades, leading to C3aR and C5aR anaphylatoxin receptors signaling, the potential targeting of C3 is a current goal in the development of complement-based therapeutics for treating chronic inflammatory and autoimmune diseases." (PMID 39684535, 2024). "Human SLE is an autoimmune disease characterized by the production of autoantibodies against nuclear and cytoplasmic antigens, accompanied by complement activation, dramatic longitudinal fluctuations in serum C4 and C3 levels, and immune-mediated tissue damage." (PMID 37932789, 2023). "The discrepancy between C3 and C4 is, we propose, a more important marker due to the C3’s central role in the complement cascade, and the fact that complement components or complement activator molecules are released and play different roles in autoimmune diseases." (PMID 35898513, 2022). "In contrast, increased levels of C3 and C4 were identified in a total CVID cohort comprised of 71 patients, 41% with autoimmune disease and 13% with granulomatous disease, as compared to 30 healthy controls." (PMID 29375540, 2017). "Patients with diagnosed thrombotic APS had significantly lower levels of C3, C4, and CH100 as well as higher percentages of activated CD4+DR+ and of CD8+DR+ T-cells than healthy controls but similar to that observed in autoimmune disease controls." (PMID 24982803, 2014). "Despite that the C3 expression in MFI remained constant (or even increased) after C1qtnf6-KO, we found its protein abundance is decreased—a sign for complement activation and assumption according to previous studies on autoimmune diseases." (PMID 41568145, 2026). "In the absence of infection or autoimmune disease, as in this patient, low C3 levels most likely reflect transient complement activation triggered by acute inflammation and hemorrhage." (PMID 40995257, 2025). "Patients also had high levels of antibodies to C3 fragments of complement and rheumatoid factors in the absence of any rheumatic or autoimmune diseases." (PMID 39765749, 2024). "Elevated levels of antibodies to C3 complement fragments (47%) and rheumatoid factors (21%) in the absence of any rheumatic or autoimmune diseases are noteworthy." (PMID 39765749, 2024). "In summary, C3 cleavage fragments promote humoral autoimmune responses, the MAC can facilitate tissue damage in the context of autoimmunity, and the chemoattractant properties of anaphylatoxins orchestrate the effector phase of many autoimmune disorders." (PMID 35958588, 2022). "TTR, ITIH4, C3, and CRP have been previously reported in the disease pathogenicity and inflammation of autoimmune diseases, affecting synovial joints with restricted joint movements, whereas HP has been linked with irregularity in the homeostasis of free hemoglobin in OA." (PMID 36569927, 2022). "There are currently several clinical trials underway using C3 inhibitors (e.g., AMY-101 and APL-2) and TLR 7/8/9 antagonists (e.g., IMO-8400) for various inflammatory and autoimmune diseases, indicating that these drugs may be readily incorporated into DMD gene therapy clinical trials." (PMID 40098958, 2025). "Sex, vitiligo type, family history of AITD, family history of other autoimmune disease, thyroid nodules or tumors, negative emotions, skin involvement exceeding 5% of body surface area, and positive immune serology (IgA, IgG, IgM, C3, and C4) were predictors of AITD in the prediction nomogram." (PMID 36798661, 2023).
autoimmune disease (continued). "Furthermore, previous studies showed that IgG and C3 were the most common immune reactants on the TBM in IF observations, whereas, our study showed that IgM and C3 were the main deposit in AIN, indicating that IC deposition in AIN and autoimmune disease might not be caused by the same mechanism." (PMID 37724528, 2023). "Follow-up during this time revealed significantly improved autoimmune disease with non-nephrotic proteinuria, low positive ANA titres and anti-dsDNA antibodies (1:80), with normal C3, C4 and white cell counts." (PMID 26951490, 2016). "Of note, significant difference in levels of anti-C1q and anti-dsDNA antibodies and complements C3 and C4 was found in patients with SLE as compared with those with a non-SLE autoimmune disease or healthy control cohorts." (PMID 26549923, 2015). "The absence of a significant reduction in C3 and CH50 may further suggest that the number of immune complexes is lower than in overt autoimmune diseases such as SLE." (PMID 39961627, 2025).
Alzheimer disease (61 papers, 2007 to 2025). A progressive, neurodegenerative disease characterized by loss of function and death of nerve cells in several areas of the brain leading to loss of cognitive function such as memory and language. "In recent studies, dysregulated C3 concentrations in CSF have been linked to various neurodegenerative disorders, such as Alzheimer's disease (AD) and dementia, via activation of C3a/C3Ra inflammatory signalling." (PMID 39426921, 2025). "Under pathological conditions such as those associated with traumatic brain injury, multiple sclerosis, and Alzheimer’s disease (AD), complement proteins, including C3, are linked to impaired cognitive functions." (PMID 38035266, 2023). "For instance, a cohort study found that low baseline plasma levels of complement C3 were associated with a high risk of Alzheimer’s disease." (PMID 35370615, 2022). "Recent studies reported that the initial component C1q and the central component C3 contribute to early synapse loss in response to Aβ and/or viral infection in Alzheimer's disease." (PMID 31032141, 2019). "The participation of astrocytes in this pathogenic process is indicated by findings that C3 secreted from astrocytes interacts with microglial C3a receptor (C3aR) to alter cognitive function in Alzheimer’s disease." (PMID 28122624, 2017). "Previous studies have demonstrated that enhanced C3/C3aR signaling promotes synaptic loss in models of Alzheimer’s disease and multiple sclerosis, whereas C3 deficiency confers neuroprotection against cognitive decline, and hippocampal CA3 synapse and neuron loss." (PMID 41321642, 2025). "Guttikonda and colleagues developed an iPSC-derived triple culture primarily for the study of secreted complement C3, as C3 has been reported to be increased under inflammatory conditions and to be implicated in neurodegenerative disorders such as Alzheimer’s disease." (PMID 37817184, 2023). "Consistent with the previously reported destructive effect of the astrocytic nuclear factor κB (NF-κB)-activated C3 secretion on dendritic morphology and neuronal function, the upregulation of C3 played a pivotal role in driving synapse loss in the aging model and several Alzheimer’s disease models." (PMID 36611988, 2023). "C3 forms part of the complement cascade and has been implicated, along with other proteins of the cascade, in several inflammatory diseases including age-related macular degeneration and Alzheimer disease." (PMID 18989387, 2008). "Because complement activation and localization of C3 and C1q complement factors in synapses has been implicated in aberrant microglia mediated synapse loss in Alzheimer’s disease (AD) models, we asked whether complement factor C1q was upregulated in the cortex of PFF-injected mice." (PMID 37848910, 2023). "Subsequent studies in murine models of Alzheimer’s disease supported the hypothesis; pathological synapse loss was reduced by inhibiting or deleting C1q, C3 or CR3, firmly implicating complement activation and opsonisation in synaptic elimination in the disease." (PMID 35794654, 2022). "GFAP/C3-positive astrocytes subpopulations have been reported in numerous brain samples from neurodegenerative disease patients such as Alzheimer's disease, multiple sclerosis, Huntington's disease, Parkinson's disease, and ALS." (PMID 40276039, 2025). "Frequently identified by upregulation of complement component 3 (C3), A1-like astrocytes have been characterized in neurodegenerative disorders like Alzheimer’s disease, with polarization correlated with disease progression and severity." (PMID 41345807, 2025). "In this study, we discovered that, similar to C1q being found at synapses in a mouse model of Alzheimer's disease (AD) 34, C3 is also located at synapses in the mPFC of CUS mice." (PMID 40860146, 2025). "The C3iKO model provides a valuable platform for understanding the role of complement C3 in age-related neurodegenerative conditions, including Alzheimer’s disease." (PMID 40678242, 2025).
Alzheimer disease (continued). "Even though neuronal C1q and C3 are normally downregulated in the adult CNS, the complement-dependent synaptic removal is thought to be aberrantly activated in Alzheimer’s disease by Aβ oligomers, thereby contributing to early synaptic loss." (PMID 38378800, 2024). "MI also elevated aggregate constituents enriched in Alzheimer’s disease (AD) aggregates, such as proteasomal subunits, heat-shock proteins, complement C3, clusterin/ApoJ, and other apolipoproteins." (PMID 37922111, 2024). "Here, we showed that C3 also localized to synapses in the mPFC after CMS exposure like C1q localizing to synapses in Alzheimer's disease (AD) mouse model." (PMID 36793870, 2023). "Accumulating evidence shows that complement C3 is present in patients of all major neurodegenerative diseases, including Parkinson’s disease, Alzheimer’s disease, Huntington’s disease, and amyotrophic lateral sclerosis." (PMID 37268807, 2023). "In Alzheimer’s disease, C3 is also expressed by microglia and C3 secreted by both microglia and astrocytes is involved in reciprocal signaling between these glial populations to produce excess C3." (PMID 36097103, 2023). "In our dataset of upregulated transcripts, we also find complement proteins (i.e., C3 and C1s2) which are known to contribute to the synaptopathy present in Alzheimer’s disease." (PMID 37143894, 2023). "More specifically, C3-knockout mice exhibited reduced anxiety, and Alzheimer’s disease model mice experienced a drop in anxiety when treated with complement inhibitors." (PMID 37783686, 2023). "Increased complement C3 was found in human cerebrospinal fluid and different brain regions in Parkinson’s disease, Alzheimer’s disease (AD), and multiple system atrophy." (PMID 37268807, 2023). "Astrocytes have been proven to express C3, and astrocyte-derived C3 regulates neuroinflammation in both Alzheimer's disease and EAE animal models." (PMID 35725556, 2022). "Aberrant protein S-nitrosylation of complement C3 contributes to the increased prevalence of Alzheimer’s disease in females." (PMID 36516243, 2022). "Recent studies have shown that amyloid-β (Aβ) directly activated astrocytic NF-κB and C3 release, consistent with the high expression of C3 seen in patients with Alzheimer’s disease." (PMID 33588866, 2021). "Apoptotic neurons activate complement pathways, and complement factors C1q and C3 are increased in Alzheimer's disease; also, in schizophrenia patients, complement factors appear to be upregulated." (PMID 30740097, 2019). "One report compared expression of mRNAs for C1q, C3 and C4 in healthy and Alzheimer’s disease (AD) brain." (PMID 29134267, 2018). "In studies on Alzheimer’s disease, C1q binding and C3-opsonization of presynaptic terminals led to pruning of synapses and was closely associated with human disease manifestation." (PMID 29743491, 2018). "In a mouse model of Alzheimer’s disease, C3 knockout reduced pro-inflammatory cytokine expressions in the brain, indicating a key role for C3 and/or its downstream signaling in cytokine productions." (PMID 30180861, 2018). "Increased levels of C3 have been found in the cerebrospinal fluid (CSF) of patients with Parkinson’s and Alzheimer’s diseases and these levels augment with the progression of the disease." (PMID 25617152, 2015). "For example, elevations in C3 mRNA expression have been demonstrated in patients with Alzheimer's disease." (PMID 17356516, 2007). "In previous studies, it has been demonstrated that a stressed, epileptic, or Alzheimer’s disease-affected brain may lead to heightened astroglial secretion of complement C3." (PMID 40294039, 2025). "Moreover, blocking C1q, C3, or the microglial complement receptor CR3 lowers the quantity of phagocytic microglia and mitigates early synapse loss in mouse models of early Alzheimer’s disease." (PMID 39682736, 2024).